CLCP2 (Charcot-Leyden crystal protein pseudogene 2)
Synonyms: LGALS10P1
Gene: Processed pseudogene on chromosome 13 (114,306,646 to 114,307,066, forward strand). Ensembl gene ENSG00000226158.
Diseases named in the same sentence as CLCP2 in open-access papers:
CLCP2 is named in the same sentence as 2 diseases in open-access papers, as found by Europe PMC text mining. Sharing a sentence is not in itself a finding about the gene and the disease. The quoted sentences say what the papers report.
gastric adenocarcinoma (1 paper, 2022). "Meanwhile, CLCP-1 and CLCP-2 in this study showed efficiently protected gastric adenocarcinoma (AGS) cells against H. pylori with the inhibition of the IL-8/NF-κB axis." (PMID 36433125, 2022).
infection (1 paper, 2022). The state of being infected such as from the introduction of a foreign agent such as serum, vaccine, antigenic substance or organism. "When the cells were treated with 1000 μg/mL of CLCP-1 or CLCP–2, about a 35% reduction in the infection rate was observed in the post-treatment of cells while it had no inhibitory activity in the other two groups, suggesting that the CLCPs directly interact with H. pylori." (PMID 36433125, 2022).